BAX (BCL2 associated X, apoptosis regulator)
Diseases named in the same sentence as BAX in open-access papers (continued):
Sharing a sentence is not in itself a finding about the gene and the disease.
glioma (continued). "However, the frequency of microsatellite instability-high (MSI-high), which results from dMMR, was low in glioblastoma, and even in gliomas with a high frequency of MSI-high, BAX gene mutations were rare." (PMID 40869124, 2025). "Furthermore, molecules like Gefitinib is reported to induce apoptosis in human glioma by affecting the BAD/BAX signaling pathway including activating caspase 9/3." (PMID 39833890, 2025). "And lower-grade glioma and liver cancer are related to the prognosis of BAX as well." (PMID 39074253, 2024). "Furthermore, DET modulates apoptosis in glioma cells by downregulating BCL2 expression while simultaneously upregulating BAX expression." (PMID 39850823, 2024). "Targeting Bcl-2 and/or activating BAX to restore caspase-3 activity may be a potential therapeutic strategy for glioma." (PMID 37185746, 2023). "Therefore, the cRGD-P/ARV-DOX micelles promoted apoptosis of glioma cells by activating the caspase cascade, down-regulating Bcl-2 expression and up-regulating BAX expression." (PMID 36157053, 2022). "As p38 MAPK-induced BAX/Bcl-2/caspase-3 apoptosis signaling is involved in glioma cell proliferation, p38 MAPK may play a pivotal role in controlling PGCs output by eliminating damaged or unscheduled pluripotency expression through mediation with Bcl-x and Bax proteins." (PMID 38911025, 2024). "Streffer and his colleagues showed that BCL-2 family protein expression (Bcl-xL and BAX) could modulate radiosensitivity in human glioma cells and targeted alterations in BCL-2 family protein expression might be a promising strategy to improve the therapeutic efficacy of radiotherapy for gliomas." (PMID 21970601, 2011). "Bioinformatics analysis using TIMER2.0 and GEPIA 2.0 revealed positive correlations between CLU expression and several genes (BAX, BCL2L1, PRNP, HSPA5, LRP2, TTR, all p < 0.05), suggesting synergistic or antagonistic interactions during glioma development." (PMID 40606578, 2025). "In glioma cells, oleuropein attenuates AKT signalling, leading to the upregulation of BAX and the downregulation of BCL-2, resulting in reduced cell viability and induction of apoptosis." (PMID 39203892, 2024). "Western blotting results indicated that HYAL2 knockdown induced Bcl-2 downregulation, an anti-apoptotic protein, in glioma cells; more importantly, HYAL2 silencing increased the level of BAX, a pro-apoptotic protein, in glioma cells." (PMID 37568202, 2023). "In conclusion, AKR1B1 has an antitumor effect on glioma cells by inducing the phosphorylated levels of p38 MAPK and thereby increasing the BAX/Bcl-2 ratio and caspase-3/7 activity." (PMID 37185746, 2023). "Nevertheless, some genes, such as BAX, IFNGR1, and PDIA3, showed a decrease in their copy number and exhibited elevated expression levels in glioma." (PMID 36428756, 2022). "The ratio of Bcl2/BAX and expression of MMP2 were increased in glioma cell with the KLHDC8A plasmid." (PMID 32851798, 2020). "PIWIL1 also regulates apoptosis and cell cycle progression through P21, Cyclin D1, BCL-2 and BAX, and migration through expression of MMP-2 and MMP-9 in glioma cells." (PMID 31443431, 2019). "PPARγ agonists was able to up-regulate pro-apoptotic protein BAX and BAD expression, and then induced glioma cells apoptosis through releasing cytochrome C and activating the activation of caspase." (PMID 29642873, 2018). "In glioma cells, Zander and coworkers described an upregulation of the proapoptotic proteins BAX and BAD and a functional role of BAX upregulation for the induction of apoptotic cell death." (PMID 23213321, 2012). "It has been reported that BA enhanced the levels of BAX and BCL-2 proteins in glioma cells and induced apoptosis in those cells." (PMID 15083202, 2004).
glioma (continued). "Therefore, we examined the expression of apoptosis-related proteins such as BAX and Bcl-2 in AKR1B1-expressing glioma cells." (PMID 37185746, 2023). "We hypothesized that the AKR1B1 reduces glioma cell proliferation and activates p38 MAPK phosphorylation, thereby mediating the Bcl-2/BAX/caspase-3 pathway." (PMID 37185746, 2023). "We found that IngC promoted modulation in proteins related to stress and cell cycle, as well as anti-apoptotic and pro-apoptotic protein expression, with special reduction in the levels of pro-apoptotic BAX, BAD, TNRI/TNFRSF1A, and FASTNFR6/CD95, were observed for most of glioma cell lines overtime." (PMID 31771098, 2019). "Moreover, curcumin induces G2/M phase arresting in glioma cell via upregulation of p21 and ING4, and further induces apoptosis through up-regulating BAX and down-regulating the Bcl-2 and NF-κB signaling pathway in glioma cells." (PMID 28671583, 2017). "To establish whether the increased expression of BAX and PUMA plays an essential role in the apoptotic death of glioma stem cells induced by the inhibition of MDM2, we knocked down BAX and PUMA and examined their effects on the apoptotic death of glioma stem cells treated with RG7112." (PMID 38612758, 2024). "The results obtained indicated that the knockdown of BAX or PUMA was sufficient to reduce cell death and inhibit caspase activation induced by the RG7112 treatment, suggesting that BAX and PUMA were both required for the apoptotic death of glioma stem cells induced by the inhibition of MDM2." (PMID 38612758, 2024). "Two hundred and eighty targets were upregulated or downregulated in 14 cancer types, among which BAX, CENPK, DLL3, and NOTCH3 showed a consistent upregulation in multiple cancers and glioma, indicating that these genes may play a carcinogenic role in a variety of cancers." (PMID 34589481, 2021). "In the present study, HDAC1 knockdown significantly increased the expression of BIM, BAX, cleaved CASPASE3 and E-CADHERIN, and suppressed the expression of TWIST1, SNAIL and MMP9, which could be interpreted to be pro-apoptosis and anti-invasion effects of HDAC1 shRNA in glioma cells." (PMID 28624794, 2017). "A detailed analysis of the effects of RG7112 on the expression of BAX, PUMA, and survivin using different concentrations showed that RG7112 increased the expression of BAX and PUMA more in glioma stem cells than in their non-stem cell counterparts." (PMID 38612758, 2024). "We then asked how TRPC6 controls POX but not BAX, p21, or PTEN expression in human glioma cells." (PMID 33508123, 2021).
pancreatic cancer (47 papers, 2003 to 2025). "Overexpression of the proapoptotic gene BAX has been reported to cause apoptosis in pancreatic cancer cells." (PMID 38554983, 2024). "In pancreatic cancer cells, δ-tocotrienol triggers EGR1 expression via the JNK–c-Jun pathway, and the upregulated EGR1 binds to the BAX promoter to initiate the expression of BAX, which causes apoptosis of pancreatic cancer cells." (PMID 33842351, 2021). "In fact, the analyzed TCGA data on breast, lung, and pancreatic cancer report that HOPS/TMUB1 expression positively correlates with the three genes of the apoptotic response: BAX, BBC3, and NOXA1." (PMID 38731819, 2024). "In pancreatic cancer PCa cells in high concentration, this compound can upregulate pro-apoptotic genes such as BAX, whereas it downregulates anti-apoptotic genes such as BCL2." (PMID 36497321, 2022). "In pancreatic cancer cells, δ-tocoptrienol triggers the EGR1 expression through the JNK/cJUN pathway, and the upregulated EGR1 binds to the BAX promoter to activate BAX expression, leading to pancreatic cancer cell apoptosis." (PMID 35727266, 2022). "A necroptosis-relevant risk model was developed for predicting pancreatic cancer survival and responses to immuno- and chemotherapy, comprising MYEOV, HDAC4, TLDC1, PITPNA, FNDC3B, HMGXB4, and BAX." (PMID 35662734, 2022). "Studies have confirmed that the pro-apoptotic gene BAX is significantly downregulated in pancreatic cancer cells with GEM acquired resistance and that the ratio of BAX/BCL-2 can predict GEM sensitivity." (PMID 35680938, 2022). "In conclusion, COL11A1 mediates apoptosis inhibition and chemoresistance in pancreatic cancer cells by activating the Akt/CREB/BCL-2/BAX signaling pathway." (PMID 33531986, 2021). "Next, we observed that AktSer473/CREBSer133 activation by COL11A1 modulates the coordinated functions of BAX/BCL-2 in decreasing the apoptotic program in pancreatic cancer cells." (PMID 33531986, 2021). "In conclusion, COL11A1 modulates apoptotic inhibition and chemoresistance in pancreatic cancer cells by activating the Akt/CREB/BCL-2/BAX signaling pathway." (PMID 33531986, 2021). "Pancreatic carcinoma genes are involved in various apoptotic processes and significantly connected on both protein and pathway levels, highlighting the BAX and survivin protein complexes, and FGFR1, SCF-KIT, and PGDF signaling pathways, respectively." (PMID 34753928, 2021). "Western blot was used to detect the expression levels of pro-apoptotic caspase-3, BAX and anti-apoptotic Bcl-2, and the results confirmed that the miR-124 mimic tempted the apoptosis in pancreatic tumor cells, which was reversed by overexpression of EZH2." (PMID 33040049, 2020). "In contrast to its transcriptional repressive function, YY1 as a transcriptional activator was shown to induce the expression of the pro-apoptotic BAX gene and induce apoptosis of pancreatic cancer cells and prevent tumor growth." (PMID 31824839, 2019). "EGR1 has been shown to act as a pro-apoptotic factor in pancreatic cancer cells through direct induction of BAX." (PMID 29719592, 2018). "For example, YY1 suppresses cell invasion and metastasis by downregulating MMP10 expression and increases apoptosis through BAX activation in pancreatic cancer cells, suggesting that YY1 functions as a tumor suppressor." (PMID 28412749, 2017). "However, the only common observation between different publications was a positive correlation between the BAX protein level and the number of apoptotic cells in pancreatic tumor tissues." (PMID 39596373, 2024). "Additionally, Egr-1 has been found to influence the expression of BAX and BCL2 in pancreatic cancer cells, with an increase in BAX and a decrease in BCL2 observed in multiple experimental conditions." (PMID 37046823, 2023).
pancreatic cancer (continued). "Additionally, our data showed that COL11A1/Akt/CREB altered the balance between BCL-2 and BAX and mediated their mitochondrial translocation in pancreatic cancer cells." (PMID 33531986, 2021). "Thus, the present findings indicate that BAX acts as a fundamental promoter of the molecular cascade by which COL11A1 mediates antiapoptotic events in pancreatic cancer cells." (PMID 33531986, 2021). "The pancreatic cancer cell line PaTu 8988t (column 2) showed strong expression of each of the proteins investigated, whereas the cell lines SW 480 and Panc-1 showed only expression of BAX, caspase-8, and caspase-9." (PMID 30686270, 2019). "Moreover, IRF-2 has been found to modulate the growth of pancreatic cancer cells by regulating proliferation and apoptosis effectors, such as cyclin D1 and BAX." (PMID 28465494, 2017). "However, the apoptosis induced by MCL-1 suppression was partially mediated through BAX in rheumatoid arthritis synovial fibroblasts and in pancreatic cancer cells." (PMID 28659182, 2017). "In addition, YY1 expression correlated with BAX expression in pancreatic cancer tissues, also suggesting that YY1 positively regulates the expression of BAX." (PMID 27074573, 2016). "We measured YY1 and BAX mRNA levels in 50 pancreatic cancer samples using quantitative RT-PCR." (PMID 27074573, 2016). "Moreover, melatonin and its metabolite N1‐acetyl‐N2‐formyl‐5‐methoxykynuramine enhanced the cytotoxic and tumor cancer cell proliferation inhibition effects of GEM in pancreatic cancer with upregulation of the BAX/BCL‐2 ratio and increased expression of active caspase." (PMID 31475468, 2019). "In pancreatic cancer, COL11A1 modulates apoptotic inhibition and chemoresistance by activating the Akt/CREB/BCL-2/BAX signaling pathway." (PMID 40927672, 2025). "Matrine in nude BALB/c mice inhibits tumor development of pancreatic cancer cells in a dose-related mode by inducing apoptosis through stimulation of CASP3, CASP8 and CASP9, reducing the BCL2:BAX ratio and upregulating FAS." (PMID 36497321, 2022). "BAX, FNDC3B, HDAC4, HMGXB4, MYEOV, and TLDC1 displayed upregulated expressions in pancreatic cancer than normal tissues." (PMID 35662734, 2022). "On the other hand, the same study suggested BAX expression as a strong indicator of longer survival (P < 0.001) even when BAX and BCL2 were found to be overexpressed in pancreatic tumour cells." (PMID 27689078, 2016). "Based on the results that miR-329 induced cell apoptosis, we next performed western blot to evaluate the expression level of apoptosis related proteins such as cleaved Caspase-3, BAX and BCL2 in the pancreatic cancer cells overexpressing miR-329." (PMID 26885689, 2016). "COL11A1/Akt disturbed the BCL-2/BAX balance, inhibiting cytochrome c (Cyt-C) release and binding of Apaf-1/procaspase-9/Cyt-C, which suppressed the apoptotic program and induced GEM resistance in pancreatic cancer cells." (PMID 33531986, 2021). "Apoptosis was induced by adjunctive use of rhein with epidermal growth factor receptor (EGFR) inhibitors in pancreatic cancer cells as verified by cell apoptosis analysis and changes in the expression level of apoptotic/anti-apoptotic proteins BCL-2, BAX, Caspase 3 and Cl-PARP." (PMID 30674340, 2019). "In the pancreatic cancer cell line Panc-1, BAX expression was not influenced by incubation with staurosporine (column 1), whereas the signal strength of caspase-8 steadily increased in a time-dependent manner (column 2)." (PMID 30686270, 2019). "The BAX gene, a member of the Bcl-2 apoptotic protein family with pro-apoptotic activity, has previously been shown to be a direct target of EGR1, which subsequently led to apoptosis induction in pancreatic cancer cells." (PMID 29719592, 2018).
pancreatic cancer (continued). "In pancreatic cancer, inhibition of either phosphatidylinositol-3 kinase or AKT led to a decreased protein level of the antiapoptotic gene BCL-2 and an increased protein level of the proapoptotic gene BAX." (PMID 26229955, 2015). "However, in pancreatic cancer, miR-365 promote the resistance to Gemcitabine, a standard chemotherapeutic agent for pancreatic cancer, by directly targeted adaptor protein Src Homology 2 Domain Containing 1 (SHC1) and apoptosis-promoting protein BAX." (PMID 24949940, 2014). "The siRNA-based knockdown of SHC1 and BAX increased gemcitabine resistance, indicating the miR-365/SHC1/BAX axis might influence the survival of pancreatic cancer cells." (PMID 24899890, 2014). "Additionally, KIFC1 depletion led to alterations in the expression of Vimentin, N-cadherin, Bcl-2, E-cadherin, and BAX, suggesting that KIFC1 may contribute to carcinogenesis and progression by influencing apoptosis in pancreatic cancer cells." (PMID 38112634, 2023). "We found that inactivation of the proapoptotic protein BAX alters its mitochondrial/cytosolic distribution and transcriptionally increases expression of the prosurvival protein BCL-2, which translocates into the mitochondrial outer membrane in pancreatic cancer cells." (PMID 33531986, 2021). "In human pancreatic cancer cells, inhibition of ERK1/2 activities caused downregulation of antiapoptotic proteins BCL-2, MCL-1, and BCL-Xl without affecting the proapoptotic proteins BAX and BAK." (PMID 27656657, 2016). "Our data show that PI3K/AKT inhibition in these pancreatic cancer cells results in a decrease in BCL-2 and an increase in BAX without effect on other members of the BCL-2 family; furthermore, this effect appears limited to those cell lines that demonstrate AKT activation under basal conditions." (PMID 12865934, 2003).